LEP (leptin)
Diseases named in the same sentence as LEP in open-access papers (continued):
Sharing a sentence is not in itself a finding about the gene and the disease.
type 2 diabetes (600 papers, 2001 to 2026). "With respect to renal function activity, an elevated serum leptin level can be attributed to impaired renal activity and an increased risk of diabetic nephropathy in individuals with type 2 diabetes." (PMID 41239622, 2025). "Antibiotic treatment has been shown to improve type 2 diabetes symptoms in leptin‐deficient (ob/ob) and diet‐induced obese mice, possibly by reducing SCFA levels, which prompts intestinal cells to use glucose to compensate for energy deficits." (PMID 40540389, 2025). "Other cardiometabolic risk factors, including type-2diabetes, insulin resistance and hypertension, have been repeatedly linked to high levels of circulating leptin." (PMID 40255297, 2025). "In obese patients, an increased level of leptin was associated with the low-grade inflammatory state, which resulted in cardiovascular diseases, degenerative disease, type II diabetes, and autoimmune disease in this group of patients." (PMID 38338780, 2024). "High levels of leptin are associated with an increased risk of type 2 diabetes, degenerative diseases, cardiovascular disease and autoimmune disorders." (PMID 39539026, 2024). "This study aimed to evaluate the association between salivary adipokine levels, including leptin, chemerin, resistin and interleukin‐6, with body mass index (BMI), waist and wrist circumference and appetite in patients with type 2 diabetes." (PMID 39539026, 2024). "In clinical studies, plasma leptin levels have been shown to be associated with insulin sensitivity in both healthy and obese women, as well as patients with type 2 diabetes." (PMID 38027100, 2023). "The db/db mice are obese and have symptoms of type 2 diabetes due to leptin gene mutation and the resulting leptin deficiency." (PMID 38203600, 2023). "In ob/ob mice, a leptin-deficient obese insulin-resistant type 2 diabetes model, leptin administration increases hydrophilic bile acids and decreases the bile acid pool." (PMID 36232990, 2022). "Of note, in our data, the association between MR-proADM and incident type 2 diabetes was attenuated when we further controlled for insulin, hsCRP and leptin." (PMID 35681200, 2022). "When women who self‐reported taking antihyperglycemic medication for type 2 diabetes were excluded from the analyses, increasing levels of leptin were associated with reduced disease‐free survival and overall survival." (PMID 35174651, 2022). "It is also unclear why only increasing levels of leptin were associated with reduced disease‐free survival and overall survival after excluding women taking antihyperglycemic medication for type 2 diabetes." (PMID 35174651, 2022). "To address this issue, we examined the effect of LF ingestion by analyzing overweight mice (Institute of Cancer Research (ICR) mice with high-fat diets; HF mice) and obese mice (leptin-deficient mice with type II diabetes; ob/ob mice)." (PMID 35267914, 2022). "For instance, in a cross-sectional study of Type 2 diabetes, plasma leptin levels were associated with coronary artery calcification (CAC), a measure of coronary atherosclerosis, after adjusting for adiposity and C-reactive protein (CRP)." (PMID 34064112, 2021). "Type 2 diabetes can be induced by a high-fat diet or genetically in the leptin-deficient mouse line." (PMID 34631683, 2021). "Elevated leptin levels are positively associated with increased type 2 diabetes risk probably due to the development of leptin resistance." (PMID 34370595, 2021). "Higher leptin levels were associated with increased risk of incident type 2 diabetes in Model 1(HR = 1.29; 95% CI = 1.05–1.58, P = 0.015), while higher adiponectin levels were associated with decreased risk (HR = 0.57; 95% CI = 0.49–0.67; P < 0.0001)." (PMID 32131811, 2020). "Cox proportional hazard regression models of incident type 2 diabetes showed a significant association between leptin, adiponectin, and incident type 2 diabetes in Model 1 (P = 0.015 and P < 0.0001, respectively)." (PMID 32131811, 2020).
type 2 diabetes (continued). "In a study in Mauritius, high leptin levels were associated with the future development of type 2 diabetes." (PMID 32131811, 2020). "Leptin was significantly associated with incident type 2 diabetes (HR = 1.55; 95% CI = 1.02, 2.36) among the abdominally non-obese, which became non-significant after adjustment for HOMA-IR." (PMID 32131811, 2020). "The leptin-deficient mouse (ob/ob), which is the classic type 2 diabetic model, and the STZ-treated mouse, which is the classic type 1 diabetic model, were used to test the hypoglycemic effect of BBR." (PMID 31976031, 2020). "Though the interaction term was not significant (P = 0.65) in Model 1, the association between leptin and type 2 diabetes was significant in men (HR = 1.33; 95% CI = 1.05–1.69) but not in women (HR = 1.24; 95% CI = 0.94–1.64)." (PMID 32131811, 2020). "Leptin has been found increased in subjects with hyperinsulinemia and type 2 diabetes, and showed a positive association with triglycerides, systolic and diastolic blood pressure." (PMID 31151171, 2019). "Leptin, a 16 kDa protein, secreted by the adipose tissue is a potential determinant of adiposity and risk for type 2 diabetes." (PMID 29422086, 2018). "Some authors postulated strong association between the adipokine ratio (high leptin/adiponectin ratio) with a higher risk of type 2 diabetes, cardiovascular disease, or insulin sensitivity." (PMID 30200554, 2018). "AGE concentrations were positively and independently associated with leptin concentrations in patients with type 2 diabetes." (PMID 30205427, 2018). "To evaluate the possible impact of these metabolic disorders in the induction of EMH, we analyzed the occurrence of EMH in a well-characterized model of type 2 diabetes, the leptin-deficient ob/ob mice." (PMID 30483254, 2018). "In general, the two mouse models (ob/ob and db/db) most commonly implemented in pre-clinical studies of type 2 diabetes/metabolic disturbances are characterized by monogenic mutations imparting dysfunction in the leptin signaling pathway." (PMID 28640857, 2017). "Visceral obesity is associated with IR, a 5.7-fold increase in leptin levels and a high risk of developing type 2 diabetes 1 year after MI onset." (PMID 26989445, 2016). "In order to address this issue, we have established a murine model of diabetic renovascular disease through placement of a cuff on the right renal artery of leptin deficient mice (db/db mice), which develop obesity and type 2 diabetes." (PMID 26925344, 2016). "Another leading edge gene in this pathway, LEP, is involved in the regulation of energy balance, and is linked to several diseases including type 2 diabetes." (PMID 26694930, 2015). "Serum leptin levels have been demonstrated to be depressed in type 2 diabetics with low bone mineral density, putting them at higher risk for bone fracture." (PMID 25789256, 2015). "It is interesting that only 4 fasting plasma markers (10- and 12-(Z,E)-HODE/LA, insulin, and leptin/adiponectin) were able predict the risk of type 2 diabetes." (PMID 26132231, 2015). "Insulin resistance in type 2 diabetes is strongly associated with leptin levels, which in turn is associated with obesity." (PMID 25789256, 2015). "On the other hand, plasma leptin levels are associated with vascular endothelial function in overweight patients with type 2 diabetes and leptin was found to be directly related to CRP independently of BMI and other confounding factors especially in men." (PMID 25994228, 2015). "Low serum leptin levels have been directly associated with low mineral density in type 2 diabetics, leading to high fracture rate of limb bones." (PMID 25789256, 2015). "Leptin and Adiponectin, which are two major hormones produced by adipose tissue and associated with type 2 diabetes, normalize insulin action." (PMID 26699937, 2015).
type 2 diabetes (continued). "While increased expression level of leptin is associated with cardiovascular diseases that lead to myocardial infarction and stroke, decreased level of adiponectin is reported in type 2 diabetes and cardiovascular diseases." (PMID 25610490, 2014). "In older men, a combination of elevated visceral fat and high leptin levels was associated with depression, and high leptin correlated positively with depressive symptoms in patients with type 2 diabetes." (PMID 25225489, 2014). "In this study, we investigated the association of plasma leptin levels with vascular endothelial function in lean and overweight patients with type 2 diabetes." (PMID 24410779, 2014). "Plasma leptin levels are associated with vascular endothelial function in overweight patients with type 2 diabetes." (PMID 24410779, 2014). "Similar mutations in leptin and the leptin receptor also occur in humans and have been linked to type II diabetes." (PMID 24618995, 2014). "Adipocytokines also contribute to the development of type 2 diabetes; for instance, leptin increases, while adiponectin decreases the risk of type 2 diabetes." (PMID 23251619, 2012). "In men and patients with type 2 diabetes, leptin levels were associated with cardiovascular disease." (PMID 22533665, 2012). "On bivariate analysis, IL-6, hs-CRP, leptin and γGT were positively associated with increased risk of type 2 diabetes; IL-1β and adiponectin were inversely associated with type 2 diabetes risk." (PMID 23251619, 2012). "As previously reported in a Finnish population as well as Japanese type 2 diabetic patients and healthy individuals, an association between leptin and CRP was observed in the Taiwanese cohort analyzed in the present study." (PMID 22533665, 2012). "In type 2 diabetes, both low and high serum leptin levels were risk factors for declining renal function." (PMID 22969168, 2012). "Down-regulation of SREBP-1c was observed in the adipose tissue of leptin deficient mice (ob/ob), in insulin-resistant humans during fasting and in response to insulin, and in adipose tissue of patients with type 2 diabetes, similar to our study." (PMID 22471940, 2012). "Cognitive deficits are thought to be associated with leptin-insensitivity in rodents and are also prevalent in humans with obesity-related diseases such as type II diabetes." (PMID 17618127, 2007). "Short sleep duration disrupts leptin regulation, resulting in decreased leptin levels and increased ghrelin levels, which elevate hunger and are linked to weight gain and an increased risk of type 2 diabetes." (PMID 41516982, 2025). "Changes in these extra-skeletal leptin target organs in the leptin signaling-deficient state can influence bone metabolism due to hypogonadism, elevated corticosteroid levels, type 2 diabetes, sarcopenia, impaired thermoregulation, and/or greatly increased body weight." (PMID 40507931, 2025). "Furthermore, in women, leptin levels were also associated with psoriatic arthritis, hypertension and, at lower extent, with type II diabetes." (PMID 40740781, 2025). "We aimed to determine whether type 2 diabetes and gestational diabetes were associated different levels of serum and cord blood adiponectin, leptin, insulin and offspring birthweight." (PMID 40045330, 2025). "We also found that fat accumulation and inflammation related to IR and type 2 diabetes were improved in the vaccine-treated group, which might be associated with the decrease in blood leptin level." (PMID 36656412, 2024). "Moreover, cross-sectional studies have reported inverse associations between these OCFA and adipokines related to type 2 diabetes risk, such as leptin and plasminogen activator inhibitor-1." (PMID 37301794, 2023). "Although our study focuses on an HFD-induced type 2 diabetes model, future research with genetically modified mice, like leptin-deficient db/db mice, may reinforce the significance of the SUMOylation pathway in DPN onset and progression." (PMID 37947589, 2023).
type 2 diabetes (continued). "There was evidence that timing of the blood collection relative to surgery and antihyperglycemic medication for type 2 diabetes may influence the associations between adiponectin and leptin, respectively, and endometrial cancer survival outcomes." (PMID 35174651, 2022). "However, in the present study, the positive association between CT-proET-1 and incident type 2 diabetes remained stable after additional adjustment for eGFR, insulin, hsCRP, leptin, and fasting glucose suggesting other possible explanations." (PMID 35681200, 2022). "Since hypoadiponectinemia has been linked to several vascular risk factors, including hypertension, coronary artery disease, heart failure, cerebrovascular disease, and type 2 diabetes, it is presumed that hypoadiponectinemia shares a vascular risk factor and causes AD with leptin resistance." (PMID 35323701, 2022). "A leptin/adiponectin imbalance may be an important risk factor of developing type 2 diabetes and cardiovascular diseases associated with abdominal obesity." (PMID 35386232, 2022). "In this study, we analyzed the SNP rs9891119 of the STAT3 gene and genetic susceptibility to type 2 diabetes involved in the leptin signaling pathway in Chinese Han population from Guangdong and explored whether there is a correlation between them." (PMID 33833859, 2021). "Elevated levels of circulating leptin may contribute to low-grade inflammation, making obese individuals more predisposed to increased risk of cardiovascular diseases, type II diabetes, or degenerative diseases." (PMID 35052684, 2021). "Deficient leptin signaling reportedly drives lipid accumulation in the liver, as has been observed in hypoleptinemic people with lipodystrophy, and in people with type 2 diabetes and leptin resistance." (PMID 35222059, 2021). "Elevated baseline leptin level is associated with the future development of type 2 diabetes." (PMID 31690939, 2020). "However, the association between leptin and type 2 diabetes was completely attenuated among abdominally obese participants." (PMID 32131811, 2020). "We found an increased risk of incident type 2 diabetes with increasing leptin levels." (PMID 32131811, 2020). "Thus, it can be concluded that the presence of abdominal obesity negates the association between leptin and type 2 diabetes." (PMID 32131811, 2020). "We hypothesized that in this sample, there would be a significant relationship between higher leptin levels and an individual’s risk of type 2 diabetes with differences by sex." (PMID 32131811, 2020). "Therefore, we aimed to discover and replicate the association between plasma leptin and 88 proteins from a multiplex proteomics assay in two independent cohorts of type 2 diabetes patients." (PMID 32753620, 2020). "Thus, our study provides useful information regarding the expected differential associations between leptin and type 2 diabetes among those with abdominal obesity." (PMID 32131811, 2020). "Moreover, in leptin-deficient (ob/ob) mice, (a model of type 2 diabetes), an increased total hepatic ceramide content has been also found." (PMID 31842461, 2019). "Both adipokines are clinically very relevant in prediabetes and diabetes, with the general perception that they exert contrary effects—leptin upregulates proinflammatory pathways which are associated with type 2 diabetes and cardiovascular disease, while adiponectin downregulates them." (PMID 30380802, 2018). "Although irisin is also secreted by adipose tissue, the reduced irisin levels in patients with type 2 diabetes may be a result of the decreased fat stores in patients with uncontrolled insulin deficiency, as is the case with leptin." (PMID 28077341, 2017). "Both leptin and insulin are known to be associated with body composition, BMI, and type 2 diabetes." (PMID 26964035, 2016).
type 2 diabetes (continued). "We sought to test the hypothesis that renovascular hypertension, induced by unilateral renal artery stenosis, exacerbates cardiac remodeling in leptin-deficient (db/db) mice, which serves as a model of human type II diabetes." (PMID 26925344, 2016). "In multiple logistic regression model, leptin has shown a significant association with obese type 2 diabetes [odds ratio (OR): 1.161, 95% confidence interval (Cl): 1.027-1.312, P < 0.05], but the significance is lost after adjusting for Age, BMI, MDA and anti-oxidant parameters." (PMID 25897417, 2015). "In multiple logistic regression analysis, leptin has shown a significant association with obese type 2 diabetes [odds ratio (OR): 1.161, 95% confidence interval (Cl): 1.027-1.312, P < 0.05], but the significance is lost after adjusting for Age, BMI, MDA and anti-oxidant parameters." (PMID 25897417, 2015). "Similarly, mice of the leptin-deficient ob/ob strain exhibit hyperglycemia and hyperinsulinemia consistent with the phenotype of type 2 diabetes and have reduced limb bone mass and length." (PMID 25789256, 2015). "Adipocytokines such as leptin and adiponectin or the proinflammatory cytokine interleukin-6 (IL-6) are affected by lifestyle habits and seem to play an important role for weight development, body composition and risk for type 2 diabetes." (PMID 24098730, 2013). "Leptin levels are associated with risk of depression onset in men with a significant amount of visceral fat and correlate positively with depressive symptoms in patients with type 2 diabetes." (PMID 24109426, 2013). "Serum leptin levels were evaluated to determine if they were associated with cardiovascular risk factors in Taiwanese adults as previously reported in men and those with type 2 diabetes." (PMID 22533665, 2012). "Leptin-deficient ob/ob mice are a model of type 2 diabetes induced peripheral neuropathy." (PMID 22412941, 2012). "Leptin-deficient ob/ob mice are widely accepted as an animal model of type-2 diabetes induced PDN." (PMID 22412941, 2012). "Consequently, we measured circulating levels of insulin and leptin by ELISA, and found them to be elevated in MyD88-deficient mice, suggesting type 2 diabetes." (PMID 20824098, 2010). "Phase II type 2 diabetes fixed-dose CagriSema (n = 31) demonstrated 15.6 % loss at week 32 with progression of −8.5 % at week four, −13.0 % at week eight, −15.1 % at week 16, and -15.6 % at week 36, showing leptin/soluble leptin receptor ratio differentiation biomarker correlations." (PMID 41255585, 2025). "Finally, as leptin has been associated with prediabetes in a dose-dependent manner, pathways related to leptin resistance in type 2 diabetes could also contribute to deficiencies in central respiratory control." (PMID 35268504, 2022). "In T2D, leptin-deficient ob/ob mice and leptin receptor-deficient db/db mice can be used as the rodent model of spontaneous type 2 diabetes." (PMID 34975496, 2021). "Furthermore, relieving ER stress with chemical chaperones, i.e., agents that have the ability to increase ER folding machinery, increases insulin sensitivity and reverses type 2 diabetes in adult leptin-deficient mice and improves leptin sensitivity in adult obese mice fed a high-fat diet." (PMID 31920985, 2019). "However, our findings may be supported by the results of large studies of type 2 diabetes risk and coronary heart disease, which have been associated with higher concentrations of leptin, resistin, and visfatin and with lower concentrations of adiponectin." (PMID 28552966, 2017). "Therefore, COS mediated inhibition of leptin secretion may lead to an anti-diabetic effect in type-2-diabetes which is associated with secretion of excessive leptin leading to hypoinsulamia." (PMID 23544120, 2013). "Protein Tyrosine Phosphatase 1B (PTP1B) is a crucial enzyme that significantly modulates insulin and leptin signaling, making it a highly promising target for the treatment of type 2 diabetes (T2D)." (PMID 41847642, 2026).